CEP63 (centrosomal protein 63)
Description:
Required for normal spindle assembly. Plays a key role in mother-centriole-dependent centriole duplication; the function seems also to involve CEP152, CDK5RAP2 and WDR62 through a stepwise assembled complex at the centrosome that recruits CDK2 required for centriole duplication. Reported to be required for centrosomal recruitment of CEP152; however, this function has been questioned. Also recruits CDK1 to centrosomes. Plays a role in DNA damage response. Following DNA damage, such as double-strand breaks (DSBs), is removed from centrosomes; this leads to the inactivation of spindle assembly and delay in mitotic progression. Promotes stabilization of FXR1 protein by inhibiting FXR1 ubiquitination.
Synonyms: FLJ13386; SCKL6
Tractability: PROTAC: UniProt records ubiquitination sites on it; ubiquitination databases record sites on it.
Gene: Protein-coding gene on chromosome 3 (134,485,699 to 134,587,789, forward strand). Ensembl gene ENSG00000182923.
Subcellular location: Cytoplasm, cytoskeleton, microtubule organizing center, centrosome; Cytoplasm, cytoskeleton, microtubule organizing center, centrosome, centriole; Cytoplasm, cytoskeleton, microtubule organizing center, centrosome, centriolar satellite
Subcellular location (Human Protein Atlas): Basal body; Centrosome; Cytosol; Nucleoplasm
Pathways (Reactome):
Cell Cycle: AURKA Activation by TPX2; Loss of Nlp from mitotic centrosomes; Loss of proteins required for interphase microtubule organization from the centrosome; Recruitment of NuMA to mitotic centrosomes; Recruitment of mitotic centrosome proteins and complexes; Regulation of PLK1 Activity at G2/M Transition
Organelle biogenesis and maintenance: Anchoring of the basal body to the plasma membrane
Gene Ontology:
Molecular function: molecular adaptor activity; protein binding
Biological process: centriole replication; negative regulation of innate immune response; negative regulation of protein K63-linked ubiquitination; protein stabilization; centrosome duplication; de novo centriole assembly involved in multi-ciliated epithelial cell differentiation; DNA damage checkpoint signaling; signal transduction in response to DNA damage; spindle assembly
Cellular component: centrosome; ciliary basal body; centriole; cytosol; spindle pole; centriolar satellite
Genetic constraint (gnomAD): Loss-of-function variants: 55 observed, 61.08 expected, observed/expected ratio (o/e) 0.9, 90% interval 0.72 to 1.13. The upper end of that interval is the gene's LOEUF score, 1.13, which puts it in group 4 of 6, group 1 being the genes least tolerant of losing a copy. Missense variants: 669 observed, 657.9 expected, observed/expected ratio (o/e) 1.02, 90% interval 0.95 to 1.08. Synonymous variants: 210 observed, 226.52 expected, observed/expected ratio (o/e) 0.93, 90% interval 0.83 to 1.04.
Homologues: Orthologues: chimpanzee CEP63 (99% identical), macaque CEP63 (96% identical), pig CEP63 (85% identical), guinea pig CEP63 (82% identical), mouse Cep63 (81% identical), dog CEP63 (81% identical), rat Cep63 (81% identical), rabbit CEP63 (78% identical), tropical clawed frog cep63 (37% identical), zebrafish cep63 (35% identical). Paralogues in human: DEUP1 (27% identical), CCDC18 (17% identical).
Diseases named in the same sentence as CEP63 in open-access papers:
CEP63 is named in the same sentence as 23 diseases in open-access papers, as found by Europe PMC text mining. Sharing a sentence is not in itself a finding about the gene and the disease. The quoted sentences say what the papers report.
microcephaly (19 papers, 2013 to 2025). A congenital or acquired developmental disorder in which the circumference of the head is smaller than normal for the person's age and sex. "Work by Phan and colleagues found that microcephaly‐associated mutations in the centrosomal genes CEP63 and CPAP cause a prolonged mitosis phenotype in neuronal progenitor cells in a mouse model for primary microcephaly." (PMID 40257113, 2025). "Mutations in Cep63 cause Seckel syndrome, a skeletal disease characterized by microcephaly and dwarfism, indicating a potential connection between Cep63 and bone formation." (PMID 38164361, 2024). "It has been also shown that CEP63 forms a complex with CEP152, another centrosomal protein implicated in microcephaly, and CEP63 deficiency leads to centriole loss due to impaired recruitment of CEP152 to the centrosome." (PMID 35805981, 2022). "A nonsense mutation in CEP63 was reported to cause Seckel syndrome in a Pakistani family, with three affected members showing microcephaly and reduced height." (PMID 34068194, 2021). "Cep63 mutation also causes microcephaly, which may affect the hypothalamus-pituitary-gonadal axis, and other cell types that support gametogenesis could also be impacted." (PMID 40294089, 2025). "Furthermore, mutations of human CEP63 were found in a primary microcephaly with defective ATR-dependent DNA damage signaling." (PMID 35805981, 2022). "Interestingly, homozygosity for a nonsense mutation in CEP63 was reported in three cousins, from a consanguineous Pakistani family, presenting with microcephaly and short stature (Seckel syndrome-6, OMIM 614728)." (PMID 26400686, 2015). "For example, mutations in the gene encoding Centrosomal Protein 63 (CEP63) or in the gene encoding Centromere Protein J (CENPJ, also called SAS4) have been found to lead to microencephaly in human." (PMID 38075281, 2023). "Moreover, mutations in Cep63 or Cep152 that disrupt Cep63•Cep152 self-assembly result in impaired centriole duplication, which could lead to chromosome missegregation and yield genetic disorders such as cancer, microcephaly, ciliopathy, and dwarfism." (PMID 37433832, 2023). "Several genes that encode for proteins implicated in centrosome function and spindle orientation are mutated in microcephaly in humans: MCPH5 or ASPM (abnormal spindle-like microcephaly associated), WDR62/MCPH2, and CEP63." (PMID 30687396, 2018). "CEP63 was demonstrated to play a key role in the recruitment of CEP152, another centrosomal protein implicated in microcephaly, to centrosomes and the artificial tethering of CEP152 to centrosomes rescued many of the cellular phenotypes of CEP63 mutant cells." (PMID 23532176, 2013). "Not surprisingly, mutations in Cep63 and Cep152 are associated with the development of human diseases, such as microcephaly and primordial dwarfism." (PMID 32810424, 2020). "We hypothesize that microcephaly-associated mutation of CEP90 causes defective centriole duplication, similar to depletion of CEP90 or of MCPH proteins such as CDK5RAP2, CEP152, WDR62 or CEP63." (PMID 26297806, 2015).
Seckel syndrome (11 papers, 2015 to 2025). A rare autosomal recessive inherited syndrome caused by mutations in the ATR gene, RBBP8 gene, CENPJ gene, CEP152 gene, CEP63 gene, NIN gene, DNA2 gene, or TRAIP gene. "Mutations in centrosomal proteins, such as CENPJ/SAS4/CPAP or CEP63, were also implicated in Seckel syndrome." (PMID 35133277, 2022). "Nevertheless, it is worth noting that CENPJ and CEP152 have been also linked with Seckel syndrome, while CEP63, which has been primarily implicated in Seckel syndrome, is also linked to MCPH." (PMID 33946187, 2021). "ASPM interacts with WDR62; this interaction is mediated by CEP63, a protein linked to Seckel syndrome, characterized by severe microcephaly with intellectual disability and short stature." (PMID 33946187, 2021). "Here, we propose that heterozygous variants of WDR62, CEP63, RAD50 and PCNT contribute to additional neurological and extra-neurological abnormalities in affected siblings of the families manifesting MCPH or Seckel syndrome." (PMID 34068194, 2021). "Seckel syndrome is genetically heterogeneous, and mutations in DDR genes (ATRIP and ATR), DNA repair factors (NSMCE2, DNA2, TRAIP and CtIP) and components of the centrosome (NIN, CEP63, CEP152 and CENPJ) have been reported." (PMID 32994318, 2020). "Other forms of Seckel syndrome are caused by mutations in genes associated with cell growth (TRAIP), genomic integrity and repair (ATR, NSMCE2, DNA2, and RBBP8), centrosome function (NIN, CEP63)." (PMID 29504900, 2018). "Ten genes have been reported for Seckel syndrome so far, and four of them (CENPJ, CEP152, CDK5RAP2 and CEP63) are also involved in MCPH." (PMID 34068194, 2021). "Here, we have provided evidence that heterozygous missense variants of WDR62, CEP63 and RAD50 aggravate the phenotype of MCPH and a PCNT nonsense variant exacerbates the severity of Seckel syndrome features." (PMID 34068194, 2021).
dyslexia (4 papers, 2015 to 2025). A learning disorder characterized by an impairment in processing written words. "Among the most recent studies that led to the identification of novel dyslexia candidate genes, it is interesting to highlight that an intronic SNP located in CEP63 was associated with WM volume in both right and left hemispheres of healthy individuals, as well as with reading comprehension scores." (PMID 34068951, 2021). "The already mentioned CEP63, identified by exome sequencing in a large family with dyslexia, is required for cilia formation." (PMID 30218584, 2018). "Moreover, the right temporoparietal region associated with rs1064395 in NCAN and also overlapped with a region previously associated with the dyslexia susceptibility genes KIAA0319, DYX1C1 and MRPL19, as well as CEP63." (PMID 34068951, 2021). "Other dyslexia candidate genes, such as PCNT, CEP63 and TUBGCP5, are involved in centrosome and basal body biology." (PMID 34068951, 2021).
ciliopathy (3 papers, 2019 to 2023). A genetic disorder of the cellular cilia or the cilia anchoring structures, the basal bodies, or of ciliary function. "Wdr62 has evidence of being a novel second order ciliopathy gene through its interaction with an intermediary protein CEP63." (PMID 36456625, 2022). "For most proteins, the trend reflected results from the WCP (i.e. PLK4 is up‐, whereas CEP63 and CEP57 down‐regulated) with the ciliopathy‐associated proteins CEP41 and CENPF being notable exceptions." (PMID 31304626, 2019).
Bladder Cancer (2 papers, 2016 to 2021). "In this retrospective study, we have focused on the prognostic value of CEP63, FOSL2 and PAQR6 in bladder cancer." (PMID 34041036, 2021). "Elevated expression of CEP63 was also correlated with poor DFS of BC patients in TCGA Bladder Cancer (BLCA) data set, which indicated the prognostic value of CEP63 on RNA levels." (PMID 34041036, 2021).
neuroblastoma (2 papers, 2021 to 2024). Neuroblastoma (NB) is the most common solid, extracranial childhood tumor. "Previous studies have documented that the upregulation of CEP63, a component of the centriole, is associated with unfavorable prognosis in cases of neuroblastoma." (PMID 38785979, 2024). "Overexpression of CEP63 leads to de novo centrosome amplification and has been associated with poor prognosis in neuroblastoma patients." (PMID 34041036, 2021). "CEP63, a constituent of the centriole, has been found to exhibit upregulation in neuroblastoma." (PMID 38785979, 2024).
Primary microcephaly (2 papers, 2013 to 2015). Head circumference below 2 standard deviations below the mean for age and gender at birth. "Centrosome function is crucial during embryonic development, highlighted by the discovery of mutations in genes encoding centrosome or spindle pole proteins that cause autosomal recessive primary microcephaly, including Cep63 and Cep152." (PMID 23936128, 2013). "Primary microcephaly (MCPH) associated proteins CDK5RAP2, CEP152, WDR62 and CEP63 colocalize at the centrosome." (PMID 26297806, 2015). "To date, mutations in nine genes encoding centrosome proteins have been identified in patients with primary microcephaly including some that are required for centriole duplication: STIL, CPAP, Cep152, Cep63 and Cep135." (PMID 23936128, 2013).
lymph node metastasis (1 paper, 2021). "Copy number gains of CEP63 were also associated with lymph node metastasis." (PMID 34041036, 2021). "Copy number gains of CEP63 were also associated with positive lymph node metastasis (p<0.01)." (PMID 34041036, 2021).
cancer (5 papers, 2019 to 2025). A tumor composed of atypical neoplastic, often pleomorphic cells that invade other tissues. "Notably, various mutations in Cep63 and Cep152 are associated with the development of diverse human diseases, including cancer and microcephaly." (PMID 30858376, 2019). "In conclusion, we found that the cancer-related CNVs of CEP63, FOSL2 and PAQR6 were competent in evaluating recurrence or progression risk for BC patients and may be used for the risk group stratifications in the future." (PMID 34041036, 2021). "HER2-enriched cancers involved four regulators of PLK1 activity at G2/M transition in the cell cycle, CEP63, CEP250, NEDD1, and HAUS3." (PMID 40700427, 2025). "The reported deubiquitinases of MYC include USP22, USP28, USP29, USP36 and USP37, and they enhance cancer stemness via BMI1, LSD1 Snail and CEP63 stabilization, respectively." (PMID 36765885, 2023).
neurological disease (2 papers, 2015 to 2021). "In addition to homozygous causal variants in ASPM or CENPJ, we discovered additional heterozygous modifier variants in WDR62, CEP63, RAD50 and PCNT—genes already known to be associated with neurological disorders." (PMID 34068194, 2021). "Developmental dyslexia is likely a neurological disease, and given the high brain expression of certain CEP63 transcripts in human, we aimed at investigating the impact of genetic variations within CEP63 on brain structure, more specifically on white matter volume." (PMID 26400686, 2015).
tumor (2 papers, 2021 to 2025). "CEP63 copy number gains (p=0.042) was also associated with high tumor grade." (PMID 34041036, 2021). "Our study also introduces a RS that integrates patient demographics, tumour characteristics, and key gene expressions such as FN1, VASP, and CEP63 to predict tumour relapse in MIBC patients undergoing NAC." (PMID 40149716, 2025). "Additionally, a risk score (RS) for predicting tumour relapse after NAC and cystectomy was calculated for each patient according to a mathematical algorithm containing FN1, VASP, and CEP63." (PMID 40149716, 2025). "Furthermore, Cox’s regression analysis showed that FN1, VASP, and CEP63 were independent prognostic factors of tumour relapse." (PMID 40149716, 2025). "Copy number gains of CEP63 (p<0.01) and FOSL2 (p=0.046) were found to be correlated with advanced tumor stage." (PMID 34041036, 2021). "Real-time PCR results showed that compared with the 49 healthy control urine sediment samples, copy numbers of CEP63 (p=0.036) and FOSL2 (p<0.01) were significantly gained in BC urine sediment samples, which was consistent with the results in tumor samples." (PMID 34041036, 2021). "Results showed that compared with the control group, copy numbers of 3 genes, CEP63 (p<0.01), FOSL2 (p<0.01) and PAQR6 (p<0.01) were significantly gained in tumor tissues." (PMID 34041036, 2021). "Copy number gains of CEP63 and FOSL2 were correlated with advanced tumor stage and high tumor grade (p<0.01 and p=0.047, respectively)." (PMID 34041036, 2021). "Copy numbers of CEP63, FOSL2 and PAQR6 were gained in 219 tumor samples." (PMID 34041036, 2021). "CNVs of CEP63 and FOSL2 were correlated with advanced tumor stage and high grade." (PMID 34041036, 2021). "CNVs of CEP63 and FOSL2 were correlated with tumor stage and histologic grade." (PMID 34041036, 2021). "Results showed that copy numbers of CEP63 (p<0.01) and FOSL2 (p<0.01) were significantly gained in 40 BC urine sediment samples compared with 42 control urine sediment samples, which was consistent with the real-time PCR results of tumor samples and 123 urine sediment samples." (PMID 34041036, 2021).
CEP63 also shares sentences with these, for which no sentence is quoted: anemia (1 paper); autosomal primary recessive microcephaly (1); dwarfism (1); genetic disorders (1); Infertility (1); male infertility (1); Nijmegen breakage syndrome-like disorder (1); ovarian carcinoma (1); primordial dwarfism (1); schizophrenia (1); Seckel syndrome 6 (1); skeletal disease (1).